MORN3 (MORN repeat containing 3)
Description:
May play a role in the regulation of spermatogenesis (By similarity).
Tractability: Small molecule: a structure with a bound ligand is known. Antibody: the Human Protein Atlas places it where antibodies can reach.
Gene: Protein-coding gene on chromosome 12 (121,648,742 to 121,672,649, reverse strand). Ensembl gene ENSG00000139714.
Subcellular location: Cytoplasmic vesicle, secretory vesicle, acrosome
Subcellular location (Human Protein Atlas): Nucleoplasm; Plasma membrane
Gene Ontology:
Molecular function: protein binding; protein-macromolecule adaptor activity
Cellular component: nucleus; acrosomal vesicle
Genetic constraint (gnomAD): Loss-of-function variants: 38 observed, 33.98 expected, observed/expected ratio (o/e) 1.12, 90% interval 0.86 to 1.47. The upper end of that interval is the gene's LOEUF score, 1.47, which puts it in group 6 of 6, group 1 being the genes least tolerant of losing a copy. Missense variants: 311 observed, 321.48 expected, observed/expected ratio (o/e) 0.97, 90% interval 0.88 to 1.06. Synonymous variants: 109 observed, 114.65 expected, observed/expected ratio (o/e) 0.95, 90% interval 0.81 to 1.12.
Homologues: Orthologues: chimpanzee MORN3 (98% identical), macaque MORN3 (97% identical), pig MORN3 (88% identical), dog MORN3 (85% identical), rat Morn3 (85% identical), mouse Morn3 (84% identical), guinea pig MORN3 (82% identical), rabbit MORN3 (81% identical), tropical clawed frog morn3 (57% identical), zebrafish morn3 (56% identical), Drosophila melanogaster CG30429 (32% identical). Paralogues in human: RSPH10B (32% identical), RSPH10B2 (32% identical), MORN1 (26% identical), RSPH1 (26% identical), ALS2CL (25% identical), SETD7 (17% identical), MORN2 (14% identical).
Diseases named in the same sentence as MORN3 in open-access papers:
MORN3 is named in the same sentence as 4 diseases in open-access papers, as found by Europe PMC text mining. Sharing a sentence is not in itself a finding about the gene and the disease. The quoted sentences say what the papers report.
cervical cancer (1 paper, 2025). A primary or metastatic malignant neoplasm involving the cervix. "Notable findings include CD70, FANCD2, PFKP, MORN3, and LEF1, which exhibited strong causal associations and potential relevance in cervical cancer pathogenesis." (PMID 40817807, 2025). "The identification of MORN3, a less characterized gene, represents a novel finding that warrants further investigation to elucidate its role in cervical cancer." (PMID 40817807, 2025).
ciliopathy (1 paper, 2025). A genetic disorder of the cellular cilia or the cilia anchoring structures, the basal bodies, or of ciliary function. "For the other two IDA-related genes (Acta2, Cfap100/Ccdc37) and one RS-related gene (Morn3), no ciliopathy has been linked to mutations of these three genes so far." (PMID 40568142, 2025).
Obesity (1 paper, 2022). Accumulation of substantial excess body fat. "Four of the differentially methylated regions were in genes previously found to be associated with obesity, metabolic regulation, and glycemic control (LRRC8D, SOSTCD1, MORN3, and MCF2)." (PMID 36474183, 2022). "Increased methylation of MORN3 and decreased methylation of LRRC8D in the context of obesity is consistent with previous studies." (PMID 36474183, 2022).
MORN3 also shares sentences with these, for which no sentence is quoted: ovarian carcinoma (1 paper).